SIRT5 (sirtuin 5)
Diseases named in the same sentence as SIRT5 in open-access papers (continued):
Sharing a sentence is not in itself a finding about the gene and the disease.
Cerebral ischemia (4 papers, 2016 to 2023). Restriction of arterial blood supply to the brain associated with insufficient oxygenation to support the metabolic requirements of the tissue. "In summary, these results demonstrated that Tat‐SIRT5‐CTM improves long‐term neurological function after cerebral ischemia." (PMID 38093788, 2023). "We also provided evidence that peptide‐induced SIRT5 knockdown is relevant to the protection of neurons from microglia‐induced neuroinflammation in an in vitro culture model of cerebral ischemia." (PMID 38093788, 2023). "The high potency of the peptide in knocking down SIRT5 in the brain and its potent neuroprotective efficacy in animal models of cerebral ischemia clearly demonstrate its effectiveness." (PMID 38093788, 2023). "Studies have shown that SIRT5 maintained mitochondrial respiration and protected against metabolic stressors and cell death after cerebral ischemia." (PMID 37627275, 2023). "To further develop Tat‐SIRT5‐CTM as a therapeutic candidate for cerebral ischemia, we then explored the safety profile of the peptide." (PMID 38093788, 2023). "Our experiments revealed that SIRT5, the major mitochondrial lysine desuccinylase, is involved in regulating mitochondrial bioenergetics and neuroprotection against cerebral ischemia." (PMID 27435822, 2016). "Furthermore, using an animal model of focal brain ischemia, we were able to show the therapeutic potential of systemic administration of Tat‐SIRT5‐CTM as a treatment for ischemic stroke." (PMID 38093788, 2023). "Actually, knockdown of SIRT5 using genetic manipulations, such as stereotaxic injection of antisense oligonucleotide or short hairpin RNA (shRNA), has been demonstrated to protect against neuronal damage in focal brain ischemia model mice." (PMID 38093788, 2023). "The main goal of this study was to investigate whether PKCε is involved in regulating SIRT3 and SIRT5 and whether these sirtuins are involved in PKCε-mediated neuroprotection following cerebral ischemia." (PMID 27435822, 2016). "Further understanding how SIRT5 is preferentially activated as well as additional pathways by which SIRT5 mediates global mitochondrial protection, could help identify a novel therapeutic intervention against cerebral ischemia." (PMID 27435822, 2016). "We wanted to determine whether SIRT5 is activated by protein kinase C epsilon (PKCε)-mediated increases in mitochondrial Nampt and whether SIRT5 regulates mitochondrial bioenergetics and neuroprotection against cerebral ischemia." (PMID 27435822, 2016).
head and neck squamous cell carcinoma (4 papers, 2017 to 2023). A squamous cell carcinoma that arises from any of the following anatomic sites: lip and oral cavity, nasal cavity, paranasal sinuses, pharynx, larynx, and salivary glands. "In particular, SIRT5 mRNA levels are increased in some cancers such as NSCLC, colorectal cancer (CRC), and Waldenstrom’s macroglobulinemia, while they are significantly decreased in others, including endometrial carcinoma and head and neck squamous cell carcinoma (HNSCC)." (PMID 36980194, 2023).
infertile (4 papers, 2019 to 2025). "The authors proposed that the dysregulation of mitochondrial sirtuins (SIRT4 and SIRT5) in the testes of obese or diabetic animals contributes to infertility by altering the acylation patterns of proteins critical for germ cell development." (PMID 41107644, 2025). "Furthermore, the different infertility diagnoses are not represented in all groups and percentages among them are notably variable; as a result, the amount of SIRT5 gene expression given is not specific for age, but just an average of the combined groups." (PMID 31906251, 2019).
ischemic stroke (4 papers, 2022 to 2025). A stroke disorder caused by obstruction of blood flow to the brain, due to thrombotic (local blood clot formation) or embolic (due to a blood clot or other material traveling from another site) event. "Collectively, our study reveals the promising efficacy of the peptide‐directed lysosomal degradation of SIRT5 and suggests it as an effective therapeutic approach for the treatment of ischemic stroke." (PMID 38093788, 2023). "Previous study identified sirtuin 5 (SIRT5) as a positive regulator of microglia‐induced excessive neuroinflammation following ischemic stroke." (PMID 38093788, 2023). "We show proof‐of‐principle evidences for the use of this Tat‐SIRT5‐CTM peptide as a potentially effective new candidate for the therapy of ischemic stroke." (PMID 38093788, 2023). "Interventions targeting SIRT5 should therefore alleviate neuroinflammation and protect against ischemic stroke." (PMID 38093788, 2023). "To investigate the neuroprotective effects of Tat‐SIRT5‐CTM in mice subjected to focal ischemic stroke injury, we first monitored cerebral blood flow (CBF) via a laser speckle imaging system." (PMID 38093788, 2023). "Frist, although shRNA‐mediated knockdown of SIRT5 has also been demonstrated to be effective in ischemic stroke models, its clinical translations are constrained by its inability to pass through the BBB." (PMID 38093788, 2023). "Our research only explored the impact of SIRT5 on the expression and release of proinflammatory cytokines; the effect of SIRT5 on microglial phagocytosis after ischaemic stroke needs further research." (PMID 36517900, 2022). "To this end, we assessed the effect of genetic overexpression and knockdown of SIRT5 on I/R-induced brain damage with a specific focus on neuroinflammation and neuronal damage using in vivo and in vitro models of ischaemic stroke." (PMID 36517900, 2022). "We provide experimental evidence that the interaction between SIRT5 and ANXA1 increases and that SIRT5 mediates the desuccinylation of ANXA1 after ischaemic stroke." (PMID 36517900, 2022). "This research systematically explored the function and potential mechanism of SIRT5 in microglia-induced neuroinflammation in ischaemic stroke." (PMID 36517900, 2022). "To assess the function of SIRT5 in ischaemic stroke, we explored the expression level of SIRT5 in vivo and in vitro." (PMID 36517900, 2022). "In the current study, we showed that SIRT5 expression in microglia was increased in the early phase of ischaemic stroke." (PMID 36517900, 2022). "Accordingly, the current research aims to explore the pathological role of SIRT5 in microglia-induced neuroinflammation after ischaemic stroke." (PMID 36517900, 2022). "Behavioural experiments also suggested that SIRT5 knockdown obviously ameliorated the learning and memorizing abilities of mice with ischaemic stroke." (PMID 36517900, 2022). "Sirtuin 5 (SIRT5) mediates lysine desuccinylation, which is involved in various critical biological processes, but its role in ischaemic stroke remains poorly understood." (PMID 36517900, 2022). "In addition, we mainly focused on the effects of Tat‐SIRT5‐CTM on microglia‐induced neuroinflammation after ischemic stroke in this study." (PMID 38093788, 2023). "However, the present study revealed that Tat‐SIRT5‐CTM targets the SIRT5‐ANXA1 complex, resulting in SIRT5 degradation via the lysosomal pathway, which eventually alleviates microglia‐induced neuroinflammation and neuronal injury following ischemic stroke." (PMID 38093788, 2023). "Our goal was to test the hypothesis that Tat‐SIRT5‐CTM is effective in protecting against ischemic stroke." (PMID 38093788, 2023). "In contrast, targeting abnormal SIRT5 has a neuroprotective effect against ischemic stroke." (PMID 38093788, 2023). "In conclusion, the fusion peptide Tat‐SIRT5‐CTM may be a promising therapeutic approach for the clinical treatment of ischemic stroke and possibly other types of neuroinflammatory disorders." (PMID 38093788, 2023).
ischemic stroke (continued). "Our findings not only establish SIRT5 as a therapeutic target for ischemic stroke but also show that the Tat‐SIRT5‐CTM peptide designed in the present study may represent a potential therapeutic candidate for ischemic stroke." (PMID 38093788, 2023). "Moreover, administration of Tat‐SIRT5‐CTM rescued neuronal loss, decreased the infarct area, and improved sensorimotor and cognitive functions after ischemic stroke in vivo." (PMID 38093788, 2023). "In this research, we have provided compelling evidence that Tat‐SIRT5‐CTM may have therapeutic promise for the clinical treatment of ischemic stroke because it rapidly decreases the protein level of SIRT5." (PMID 38093788, 2023). "Although the effects of SIRT5 on the CNS have been introduced, whether SIRT5 also functions in the pathophysiology of ischaemic stroke remains poorly characterized." (PMID 36517900, 2022). "Collectively, our data identified that SIRT5 inhibition might represent a potential therapeutic strategy for ischaemic stroke." (PMID 36517900, 2022). "Whether SIRT5 is also involved in regulating microglial phagocytosis after ischaemic stroke remains unclear." (PMID 36517900, 2022). "Interventions targeting SIRT5 expression may represent a potential therapeutic target for ischaemic stroke." (PMID 36517900, 2022). "Importantly, systemic administration of Tat‐SIRT5‐CTM reduced the brain infarct area and neuronal loss, mitigated neurological deficit scores, and improved long‐term neurological functions in a mouse model of ischemic stroke." (PMID 38093788, 2023). "Therefore, a new SIRT5 knockdown approach involving peripheral delivery of an agent that can efficiently cross the BBB might be a promising treatment for ischemic stroke." (PMID 38093788, 2023). "Thus, the fusion peptide Tat‐SIRT5‐CTM may be a promising therapeutic candidate for the treatment of ischemic stroke." (PMID 38093788, 2023). "Previous studies have shown that SIRT5 plays vital roles in the regulation of autoimmune responses, cell division, metabolism, genome stability and cellular senescence, but little research has been done on whether and how SIRT5 functions in ischaemic stroke." (PMID 36517900, 2022). "We hope that this Tat‐SIRT5‐CTM peptide can also be successfully translated to the clinic as a new and effective treatment for ischemic stroke in human patients." (PMID 38093788, 2023). "In summary, our investigation confirmed that a small peptide, Tat‐SIRT5‐CTM, specifically inhibits neuroinflammation following ischemic stroke." (PMID 38093788, 2023). "Our previous study showed that SIRT5 bound to and desuccinylated ANXA1 at K166, which was sufficient to induce neuroinflammatory and neurological function damage after ischemic stroke." (PMID 38093788, 2023). "In contrast, suppression of SIRT5-mediated desuccinylation of ANXA1 effectively inhibits neuroinflammation and improves neurological function after ischaemic stroke." (PMID 36517900, 2022). "Thus, SIRT5 might be a promising therapeutic target for the treatment of ischaemic stroke." (PMID 36517900, 2022). "Additionally, SIRT5 regulates ferroptosis through NRF2/heme oxygenase‐1 signaling and participates in ischemia–reperfusion injury in ischemic stroke." (PMID 39713961, 2025). "A novel cell-penetrating peptide, Tat-SIRT5-CTM, has been developed to selectively induce lysosomal degradation of SIRT5 in microglia, thereby mitigating microglia-driven neuroinflammation after ischemic stroke." (PMID 41007413, 2025). "Furthermore, in vitro and in vivo evidence revealed that Tat‐SIRT5‐CTM reduced neuronal damage and the infarct volume and improved long‐term neurological functional outcomes following ischemic stroke." (PMID 38093788, 2023). "Importantly, improving SIRT5 significantly promotes ANXA1 nuclear translocation and suppresses ANXA1 membrane recruitment, followed by microglial hyperactivation, ultimately leading to excessive neuroinflammation and neuronal damage after ischaemic stroke." (PMID 36517900, 2022).
Listeria monocytogenes infection (4 papers, 2018 to 2024). "SIRT5 deficiency did not sensitize mice to severe S. pneumoniae pneumonia, rapidly lethal E. coli peritonitis, listeriosis and staphylococcal infection." (PMID 30515162, 2018). "Herein, with adoptive transfer of Sirt5+/+ or Sirt5−/− OT-1 cells and acute Listeria monocytogenes infection model, we demonstrate that SIRT5 deficiency does not affect CD8+ T cell effector function and that SIRT5 is not required for CD8+ T cell memory formation." (PMID 34966740, 2021). "Furthermore, SIRT5 deficiency did not worsen endotoxemia, pneumonia caused by Klebsiella pneumoniae or Streptococcus pneumoniae, Escherichia coli-induced peritonitis, listeriosis, and staphylococcal infection." (PMID 34925356, 2021). "Moreover, preclinical models suggest that SIRT5 deficiency does not worsen endotoxemia, Klebsiella pneumoniae and Streptococcus pneumoniae pneumonia, Escherichia coli peritonitis, listeriosis, and staphylococcal infection." (PMID 30515162, 2018). "Herein, our present study aimed to explore the effects of SIRT5 on the effector function and memory differentiation of CD8+ T cells with OT-1 TCR transgenic mice and acute Listeria monocytogenes infection model." (PMID 34966740, 2021). "As SIRT3 and SIRT5 share the similar subcellular location and targets, maybe due to their compensated functions, neither Sirt3 nor Sirt5 knockout altered host defenses against bacterial infection, but dual deficiency of SIRT3 and SIRT5 exhibited a modest protection against listeriosis host defense." (PMID 34966740, 2021). "During acute listeriosis, SIRT5+/+ and SIRT5−/− mice displayed similar bacteremia (SIRT5+/+ vs. SIRT5−/−: 4.1 ± 2.2 × 103 CFU/ml vs. 4.8 ± 3.6 × 103 CFU/ml; mean ± SEM, P = 0.8) and survival rate (P = 0.9) (plain lines)." (PMID 30515162, 2018). "Going well along with these observations, preclinical models revealed that SIRT5 knockout mice are not particularly sensitive to endotoxemia, Klebsiella pneumoniae and Streptococcus pneumoniae pneumonia, Escherichia coli peritonitis, listeriosis and staphylococcal infection." (PMID 30515162, 2018).
steatosis (4 papers, 2020 to 2024). Increased lipid within the cytoplasm of cells. "Background/Objectives: This study evaluated the association between polymorphisms in the PNPLA3, TM6SF2, HSD17B13, and SIRT5 genes and the severity of fibrosis and steatosis in metabolic dysfunction-associated steatotic liver disease (MASLD)." (PMID 39596570, 2024). "Loss of either Sirt5 or the mitochondrial FAO enzyme LCAD pushed the phenotype into macrovesicular steatosis in the periportal zone." (PMID 33110171, 2020). "For predicting fibrosis, selected parameters in the univariate analysis included age, T2DM, HT, AST, platelet count, steatosis grade, and PNPLA3 and SIRT5 variants." (PMID 39596570, 2024). "(2020) reported that feeding Sirt5 knockout mice, which lack a lysine desuccinylase that regulates fatty acid oxidation and ketogenesis, an HFD containing high amounts of C12 found in coconut oil for 5 weeks resulted in periportal macrovesicular steatosis." (PMID 38192209, 2024). "Interestingly, replacing C12 with MCT oils, containing 60% C8 and 40% C10, for the same duration, did not produce overt macrovesicular steatosis, although a modest degree of microvesicular steatosis was observed in Sirt5 knockout mice when fed MCT oils." (PMID 38192209, 2024).
subarachnoid haemorrhage (4 papers, 2022 to 2025). "However, other studies showed that SIRT5-mediated desuccinylation of lysine protected against mitochondrial metabolic disorder in mice after subarachnoid haemorrhage." (PMID 36517900, 2022).
type 2 diabetes (4 papers, 2021 to 2025). "One study revealed that SIRT5 is downregulated in the pancreas of mice suffering from type 2 diabetes mellitus (T2DM), and plays a role in maintaining β-cell mass and function in glucolipotoxic conditions, retaining insulin secretion." (PMID 33806509, 2021). "SIRT5 expression is upregulated in pancreatic β-cell lines in patients with type 2 diabetes (T2D), and its expression level is positively correlated with age and blood glucose levels, and negatively correlated with pancreatic and duodenal homeobox 1 (PDX1) expression." (PMID 39979670, 2025).
Alzheimer disease (3 papers, 2022 to 2025). A progressive, neurodegenerative disease characterized by loss of function and death of nerve cells in several areas of the brain leading to loss of cognitive function such as memory and language. "The findings indicated that SIRT5 desuccinylated and activated RAB7A at the K31 residue to rescue the cadmium‐provoked Alzheimer's disease progression by restoring the autophagic flux, and identified potential targets for the treatment of environmental contaminant‐associated brain degeneration." (PMID 38837686, 2024).
colorectal tumor (3 papers, 2020 to 2025). "Mouse colon sections were H&E-stained, and histologic evaluation of the severity of inflammation and dysplasia/neoplasia revealed that WT mice suffered more serious colorectal tumors than Sirt5 KO mice." (PMID 32953892, 2020).
COVID-19 (3 papers, 2022 to 2025). A disease caused by infection with severe acute respiratory syndrome coronavirus 2. "Overall, thisstudy uncovered an unusual type of interaction and points toward thekey role of SIRT5 in viral replication, suggesting that SIRT5 inhibitioncould be a useful strategy to combat COVID-19, most likely in combinationwith other therapeutics." (PMID 35802779, 2022). "The current findings suggest that SIRT5 may be a potential drug target against COVID-19." (PMID 39979670, 2025). "Inhibiting SIRT5 will probably never represent a first line of defense, but it could be used in combination with drugs that directly target viral enzymes, leading to novel therapeutic regimens against COVID-19." (PMID 36095012, 2022).
epilepsy (3 papers, 2016 to 2023). A brain disorder characterized by episodes of abnormally increased neuronal discharge resulting in transient episodes of sensory or motor neurological dysfunction, or psychic dysfunction. "Further investigations are needed to encode the natural property of SIRT5 in mitochondria and their contribution in epilepsy and neurodegeneration." (PMID 27445698, 2016). "In the present study, we provided strong evidences for the first time to demonstrate the association between SIRT5 and epilepsy, which offers a new understanding of the roles of SIRT5 in mitochondrial functional regulation." (PMID 27445698, 2016). "After a single seizure episode, sirtuin 5 increases in our PTZ model of epilepsy, with similar effect observed in the kainate model." (PMID 36293175, 2022). "The effect of SIRT5 on mitochondrial metabolism and function implies the potential positive correlation between SIRT5 and epilepsy." (PMID 27445698, 2016). "The present study will provide the evidence for the important role of SIRT5 on KA-induced seizure and epilepsy by using genetic ablation of SIRT5 in mice." (PMID 27445698, 2016). "No report demonstrated the association of SIRT5 with epilepsy and the contribution of SIRT5 in the pathogenesis of seizure and of epilepsy." (PMID 27445698, 2016). "Our findings unravel involvement of SIRT5 and OGDH in metabolic adaptation to seizures through protein acylation, consistent with the known neuroprotective role of SIRT5 and contribution of OGDH to the Glu/GABA balance perturbed in epilepsy." (PMID 36293175, 2022). "In a rat model of pentylenetetrazole (PTZ)-induced epilepsy, we quantify 43 acylations in 29 cerebral cortex proteins; levels of NAD+; expression of NAD+-dependent deacylases (SIRT2, SIRT3, SIRT5); activities of the acyl-CoA-producing/NAD+-utilizing complexes of 2-oxoacid dehydrogenases." (PMID 36293175, 2022). "Significantly, SIRT5−/− mice exhibited much higher mortality rate to systemic injection of KA in a dosage-dependent manner, indicating the possible role of SIRT5 and its regulation in the process of epilepsy." (PMID 27445698, 2016).